CD68 (CD68 molecule)
Diseases named in the same sentence as CD68 in open-access papers (continued):
Sharing a sentence is not in itself a finding about the gene and the disease.
tumor (continued). "In addition, high BGN expression was significantly associated with tumor invasion depth (p < 0.001), lymphatic vessel invasion (p = 0.001), and increased expression of CAF markers, αSMA (p = 0.003) and FAP (p = 0.022), and macrophage markers, CD68 (p = 0.049) and CD163 (p = 0.007), in ESCC tissues." (PMID 41465449, 2025). "M2 TAMs, characterized by a CD68+/CD163+ phenotype, release cytokines that deplete tumor-infiltrating lymphocytes (TILs), inactive killer T cells and facilitate tumor immune evasion." (PMID 40539047, 2025). "Integrative analysis showed that the most dominant pairwise cell-cell contacts in mFGFR2 iCCA were between tumor cells and CD11b+/CD15+ granulocytes as well as between tumor cells and αSMA+ fibroblasts and CD68+/CD163- macrophages." (PMID 39969434, 2025). "Tumor infiltrating CD8+, CD138+, CD68+ cells and CD68+/CD8+ ratio according to clinical, biochemical, morphological, and pathological features of the whole study cohort." (PMID 40789673, 2025). "In the 4C analysis, we found that high infiltration of CD68+CD163+ macrophages correlated with improved DFS, particularly in the stromal compartment of tumor distant normal tissue." (PMID 40498004, 2025). "We collected tissue samples from 11 HCC patients and used PanCK to mark tumor cells, CD45 to delineate the intra-tumoral immune cells, and CD68 to identify macrophages." (PMID 40467555, 2025). "Our benign samples from LTT had lower CD68 levels, but DHT-treated BC samples had higher CD68 levels in tumor stroma." (PMID 40729351, 2025). "Immunostaining for CD8 and CD68 confirmed that infiltration of CD8+ T cells and macrophages was increased in the tumor tissues of the combo group." (PMID 40995650, 2025). "In the tumor progression from non-invasive to invasive cancer, infiltration of endothelial cells (PECAM1) and macrophages (CD68) was noted in the tumor interior, in addition to increased chemokine signaling (CXCR4)." (PMID 39965034, 2025). "Multiplex immunofluorescence accordingly revealed that primary tumor tissues from mice treated with combination ICT showed a significant increase in tumor cells co-expressing GFP (marker of tumor cells) and myeloid markers such as S100A9, CD68, and F4/80." (PMID 41290625, 2025). "The number of tumor infiltrating CD8+ lymphocytes was 13/HPFs (IQR: 16.3), of CD68+ macrophages was 56/HPFs (IQR: 40.8), and of CD138+ lymphocytes was 4/HPFs (IQR: 6)." (PMID 40789673, 2025). "In order to evaluate the expression levels and topographic distribution profiles of CD4, CD8, Foxp3, CD68, CD163, and CD11c, tissue microarrays of the invasive front as well as the tumor core of BCC and cSCC samples were analyzed." (PMID 41068337, 2025). "We stained the tumor tissue sections with five markers, α-SMA, GLUT1, CD68, ICAM1, and GPNMB, to exclude the possibility of simultaneous expression of ICAM1 and GPNMB by the same MDMs." (PMID 41174767, 2025). "Consistent with this, the regressing tumor exhibited a reduction in cell staining for lymphocyte markers such as CD3, CD4, and CD8 as well as the monocyte/macrophage marker CD68." (PMID 40594889, 2025). "Our analysis revealed increased abundance of most cell types in tumor areas, including conventional T cells, Treg cells, and both CD206−MHCII+CD68+ M1-like and CD206+MHCII−CD68+ M2-like macrophages." (PMID 40588561, 2025). "CD68, however, was co-expressed with ANXA1 throughout on the majority of TAMs, both in the stroma and in tumor nests." (PMID 40361334, 2025). "The corresponding heatmap depicted the high-expression profiles of various cell types in marker genes such as KRT19, VWF, ACTA2, CD68, and TPSB2, effectively distinguishing immune, stromal, and tumor cell components." (PMID 41488617, 2025). "The expression patterns of CD68, CD86, and CD163 were first analyzed to assess differences between the tumor nest and tumor stroma." (PMID 40510346, 2025).
tumor (continued). "The number of CD68- and CD34-positive cells per 1.38 × 105 μm2 in the deepest infiltration zone and tumor center, respectively, was measured at multiple locations in each case, and the mean values were determined." (PMID 40243510, 2025). "CD68+ staining was prominent throughout the TME, particularly at the tumour-bone interface and the tumour periphery." (PMID 41315643, 2025). "Immunohistochemistry revealed positivity for CK and CD68, scattered Ki-67-positive cells, and TRPS1 positivity, indicating tumor cell infiltration." (PMID 40797399, 2025). "To investigate the intra-T and peri-T topography and the link of macrophages (CD68+) and tumor B cells (CD20+) with CD86 and CSF1-R expression, we performed IF staining of DLBCL and non-tumor control samples in the same TMAs." (PMID 41415285, 2025). "The 5-plex staining showed that all tested cell types - tumor cells (Pan-Cytokeratin; PCK), macrophages (CD68), B-cells (CD20) and cytotoxic T (CD8) and T-helper (CD4) cells - were present in the tested samples." (PMID 40845489, 2025). "The results showed that CD19‐81‐293‐EXO treatment recruited similar levels of CD45+ leukocytes; CD68+ macrophages and monocytes; CD11c+ dendritic cells; and CD3+, CD4+, and CD8+ T cells into the tumor compared to the control group." (PMID 40985609, 2025). "Additionally, correlations between CD68 expression and six TIICs (B cells, CD4+ T cells, CD8+ T cells, macrophages, NK cells, and cancer-associated fibroblasts) or four common TICs (PDCD1, CTLA4, IDO1, and CD40) were assessed using the Tumor Immune Estimation Resource (TIMER)." (PMID 40918116, 2025). "Among these markers, CD68 and CD163 are two important indicators that are related to the tumor microenvironment (TME)." (PMID 41256322, 2025). "The tumor exhibited diffuse positivity for S-100, SOX10, MITF, TRIM11, and CD68, along with focal positivity for HMB45, MelanA, and CD99, while being negative for ALK." (PMID 40491616, 2025). "We analyzed CD68 mRNA and protein expression using online databases and immunohistochemistry (IHC) on tissue microarray (TMA) sections, comparing DSC tumor tissues with adjacent normal tissues." (PMID 40918116, 2025). "Assessment of tumor immunogenicity by immunohistochemistry revealed the following number of immune cells: CD8+ cells - 11 per 1 mm2, CD68+ – 6 per 1 mm2, CD163+ macrophages – 3 per 1 mm2." (PMID 39936166, 2025). "Our results showed that CD68+ and CD163+ TAMs were more abundant in the tumor mucosa than in the normal mucosa, with higher levels in late-stage CRC." (PMID 41573553, 2025). "We further characterized non-tumor TIM-3 positive cells with additional broad immune markers (CD3, CD4, CD8 and CD68)." (PMID 39953623, 2025). "Multiplex immunohistochemistry was used to identify CD68+PD‐L1+ and CD3+PD‐1+ immune cells and PD‐L1 expression on tumor cells." (PMID 39783790, 2025). "Along these lines, it has been shown that LAIR1 is associated with stroma and strongly expressed in several human tumors, mainly on myeloid CD68+ SMA+ cells with suppressive functional features in human tumor and tumor murine models." (PMID 40563506, 2025). "Over 50% of immune cells were CD68+ macrophages, predominantly CD68+HLA-DR−CD163− M0 and CD68+CD163+ M2 subtypes over the CD68+HLA-DR+ M1 subtype, suggesting a pro-tumor and immunosuppressive TME." (PMID 40940877, 2025). "Markers for T-cell subsets (CD4, CD8), macrophages (CD68, CD163), granulocyte cells (CD11b), tumor cells (PanCK), vasculature (CD31), and epithelium (cytokeratin) were clearly visualized in the CODEX fluorescent images." (PMID 39969434, 2025). "The Wilcoxon test revealed a significant difference in the expression of the markers CD68, CD86, and CD163 between the tumor nest and tumor stroma in both the primary tumor and brain metastases across the overall cohort (p < 0.0001)." (PMID 40510346, 2025).
tumor (continued). "Assessment of tumor immunogenicity by immunohistochemistry revealed the following number of immune cells: CD8+ cells - 15 per 1 mm2, CD68+ – 7 per 1 mm2, CD163+ macrophages – 35 per 1 mm2." (PMID 39936166, 2025). "In BRCA, although tumor tissue partially expressed more SLC19A1, the single-CD68-positive cells indicated the majority of infiltrated immune cells were macrophages or monocytes instead of M2 macrophages." (PMID 40149548, 2025). "While CD68+ macrophages were mostly found in the intratumoral region, the CD163+ macrophages prevailed within the tumor stroma." (PMID 41150099, 2025). "Subsequent subclustering of CD68+CD206+MARCO+ AMs identified eight distinct clusters present across both normal and tumor tissue." (PMID 41567211, 2025). "The use of six specific IHC markers—CD20, CD5, CD8, CD68, CD23, and CD45—is based on their established roles in lymphocyte differentiation, tumor microenvironment characterization, and specific disease pathologies relevant to the study's focus." (PMID 40134445, 2025). "To confirm our TAM and Treg cell transcriptional findings, we evaluated pretreatment tumour samples (n = 27) using multiplex immunofluorescence staining for pan-cytokeratin (tumour marker), FOXP3 (Treg cell marker), CD68 (macrophage marker) and PD-L1." (PMID 38418879, 2024). "VISTA is predominantly expressed on TME-infiltrating myeloid cells (i.e., MDSCs and CD68+ TAMs), CD4+ and CD8+ T cells, and tumor cells." (PMID 38357542, 2024). "IHC established tumor (PanCK) and stromal regions (fibroblast activation protein, FAP) of the tumor, as well as cytotoxic T cell (CD8) and macrophage (CD68) infiltration." (PMID 38517140, 2024). "To investigate alterations in tumour metabolism and microenvironment, we performed immunohistochemical staining for FABP4, CD36 and CD68." (PMID 38926671, 2024). "The CD68+SHP2+ subset proportion was positively correlated with the CD68+CD206+ subset within TME (P < 0.0001), tumor (P < 0.0001) and stroma (P < 0.0001)." (PMID 38799432, 2024). "The numbers of both, CD68+ and CD163+ cells, were significantly increased in tumor-adjacent adipose tissue in overweight/obese patients." (PMID 39456610, 2024). "The markers used to characterize the immune and tumor compartments of the iTME were: CD3, CD4, CD8a, FOXP3, PD-1, PD-L1, CD68, CD33, and pan-keratin (PanCK)." (PMID 38898200, 2024). "The mean numbers of CD68+ and CD163+ infiltrating macrophages in both the tumor nests and stroma were concordantly higher in LLT1-positive tumors compared to LLT1-negative tumors." (PMID 38673902, 2024). "We developed a novel immunohistochemical panel to assess prognostic outcomes and treatment sensitivity by detecting the expression of VCAN, CD3G, C1QB, CD68, CD4, and CD8 in both the TME and tumor cells of 190 DLBCL patients." (PMID 38980810, 2024). "High grade tumors had a significantly higher infiltrate of FoxP3+ cells (p = 0.02), CD68+ cells (p = 0.01), CD163+ cells (p = 0.01), LAG3+ cells (p = 0.01), PD1+ cells (p = 0.01) and TIM3+ cells (p = 0.03) when compared with low grade tumours." (PMID 38691575, 2024). "The CD68+SHP2+ subset proportion was positively correlated with the M2 subset within TME, tumor and stroma." (PMID 38799432, 2024). "Immunohistochemistry showed that tumor cells positively expressed vimentin, SMA, and Desmin usually, and CK, CD68, CD30 and ALK were partially expressed positively, while CD117 and CD34 were usually negative expressed." (PMID 39193013, 2024). "Numerous studies have demonstrated a significantly higher number of CD68+ macrophages and CD163+ M2-like phenotypes in the tumor mass and within infiltrative areas of glioblastoma patient post-bevacizumab therapy." (PMID 38787372, 2024). "Immunohistochemistry reveals tumor cell positivity for CD30, CD68, CD163, ALK1, ALK (D5F3), and EMA; Genetic testing shows ALK gene rearrangement in tumor cells but with different ALK fusion partners, mainly SQSTM1 (52%) and VCL (30%)." (PMID 38706599, 2024).
tumor (continued). "We observed colocalization of IDO1, PD-1, CD68 (marker of TAMs), and CD163 (marker of M2 macrophages) in the tumour stroma." (PMID 39351094, 2024). "To investigate the spatial connection of SPP1 + SIRPα + macrophages with tumor cells and CD8 + T cells, we conducted in-situ mIHC staining in 39 ESCC patients from ESCC cohort 1 using antibodies against CD68, SIRPα, SPP1, panCK, PD-1, and CD8." (PMID 39696410, 2024). "Regarding CD68 expression, incidence curves for CD68 POS showed a clear ordering of incidence curves for CRC‐specific death, but in opposite directions for tumor and tumor‐adjacent tissues." (PMID 36811271, 2024). "Since MIP-1β is produced by macrophages, the correlation between MIP-1β and the density of macrophages (CD68 and CD163) in the tumor microenvironment was evaluated." (PMID 38339307, 2024). "The analysis of ESCC clinical samples indicated that in the majority of tumor tissues with low expression of LINC00330, there was a significant increase in CD68+ TAM infiltration." (PMID 38769475, 2024). "Supporting an increased immune response, we found higher numbers of CD68+ and CD163+ (M2-like) macrophages in the tumor-adjacent adipose tissue of overweight/obese TNBC patients." (PMID 39456610, 2024). "In tumor tissue segments, CD45+ immune cell and CD68+ macrophage infiltration, as well as Ki67 expression for proliferation, was not significantly altered in the primary tumors and bone metastases." (PMID 38193534, 2024). "IHC analysis of 12 pairs of randomly selected CRC samples showed a positive correlation between the proportion of RUNX1 positive areas and CD68 (P < 0.0001), CD163 (P = 0.0002) positive areas in tumor." (PMID 38419056, 2024). "In the tumor‐adjacent mucosa, an increased Rep INT was correlated with an increased CD68 INT (r = 0.236, P < 0.001)." (PMID 36811271, 2024). "This study showed that elevated expression levels of CD47, CD68, and CD163 in tumor tissues are significantly correlated with poorer OS and PFS in patients with NPC." (PMID 39682556, 2024). "When focused on the tumor location, the right-sided CRC showed increased level of fibroblasts and CD68+ cells, and reduce in the neutrophil population." (PMID 38951801, 2024). "Patients with higher scores had increased CD8+ T cells and decreased CD68+ cells after CCRT in the TME which we had termed immune-inflamed TME (i.e., “hot” tumor)." (PMID 38654284, 2024). "CD68 and CD163 expression varied across tumor sections, with some showing strong positivity and others resembling atypical ALK-rearranged histiocyte-rich tumors." (PMID 39867882, 2024). "The first panel featured staining for tumor cells (pan-CK+), B cells (CD20+), CD4+ and CD8+ T cells, Tregs (CD4+FOXP3+), and macrophages (CD68+)." (PMID 38994676, 2024). "We subsequently tested the epithelial membrane antigen (EMA), vimentin, CD68, and CD163 in tumor tissues, all of which showed positive expression." (PMID 39432588, 2024). "We furtherly double-stained macrophages (CD163+ CD68+), helper T cell (CD3+ CD4+), cytotoxic T cell (CD3+ CD8+), and Treg cell (CD4+ FOXP3+) of subcutaneous tumor tissues and examined the cells using immunofluorescence (IF)." (PMID 38483163, 2024). "An association between BMMF Rep and Mf detection levels was analyzed by correlation analysis of Rep and CD68 staining based on INT and POS and performed separately for both tumor‐adjacent mucosa and tumor tissues." (PMID 36811271, 2024). "An eleven-marker panel (CD3, CD4, CD8, FOXP3, CD68, arginase-1, CD33, HLA-DR, pan-keratin (PanCK), PD-1, and PD-L1) was used to study the tumor and immune cell compositions." (PMID 38898200, 2024). "Notably, CD68+ macrophage levels decreased from baseline in all three biopsy pairs, which suggests that treatment with mivavotinib impacts the myeloid lineage within the tumor and may result in the depletion of TAMs." (PMID 38501219, 2024).
tumor (continued). "Second, tumoral tissues are often enriched with immune suppressive cells such as CD68+CD163+ macrophages and T regulatory cells, and we show that tumor cells spatially surround themselves with immune suppressive cells." (PMID 38575670, 2024). "PD-L1 and tumor microenvironment (CD4, CD8, CD68 and CD163) expression were investigated in LSCC using immunohistochemistry." (PMID 39123373, 2024). "Tumor infiltration by immune cells, particularly CD8+ lymphocytes and CD68+ macrophages, has been recognized as a significant prognostic factor in lung cancer." (PMID 39330005, 2024). "In co‐immunofluorescence analysis as well as in the analyses on consecutive cuts of the tumor‐adjacent mucosa of the TMA, the tissue regions showing high Rep expression were overlapping with the regions with high CD68 expression." (PMID 36811271, 2024). "Paraffin-embedded, formalin-fixed tumour tissue blocks of 138 patients representative of the population and including early stage disease were identified, stained for CD3, CD20, CD68 and CD163 and analysed for both the stromal and intertumoral components." (PMID 38674108, 2024). "Baseline tumor PD-L1 and IRF1 nuclear expression (both in CD3 + T cells and in CD68 + cells) were higher in responding patients." (PMID 38519913, 2024). "Higher numbers of CD4+ T cells, CD8+ T cells, CD20+ B cells, CD68+ macrophages, LAMP3+ DCs, PD-L1+ cells, and TLSs were detected in patients with a single tumor than in those with multiple tumors." (PMID 38254190, 2024). "Subsequently, immunostaining of the left tumor revealed HHF-35, CD68, and ALK-1 positivity, and this tumor was also diagnosed as IMT." (PMID 39516994, 2024). "To analyze the characteristics of the TIME in different tumor regions, we first detected the expression of immune markers including CD4+, CD8+, Foxp3+, CD20+, CD68+, LAMP3+, PD-1+ TILs, and PD-L1 in different tumor regions using IHC." (PMID 38254190, 2024). "To confirm their identity, firstly we performed IHC with standard immune cell markers (CD45, CD68, and CD8) and S100A9 on tumor sections, distinguishing tumor core and necrotic areas." (PMID 38411438, 2024). "We also analysed the presence of tumor-infiltrating immune cells: T cells (CD3A+) and macrophages (CD68+)." (PMID 39428471, 2024). "Expression levels of CD68, representing all TAMs, and of CD4 were consistently and highly expressed throughout all stages of tumor progression, whereas CD8A expression was increased in later disease stages." (PMID 38618956, 2024). "Then we used Loupe Browser 7.0 to group spots with gene characteristics (log2 count > 0) of CD68 or CD4 with CTLA4 as THC, and spots with gene characteristics of CD3D or CD3E or CD3G as tumor immune cells." (PMID 39499374, 2024). "In this case, the tumor demonstrated a significant immune response with high levels of CD163 (3+), CD68 (3+), PDL-1 (2+), CD3 (3+), and CD8 (3+) infiltrating cells." (PMID 39335193, 2024). "Our research utilized immunofluorescence techniques to gauge Mannose/CD68 and CD34/Mannose expression within tumor cohorts and appraised iNOS/CD68 and Mannose/CD68 expressions in macrophages." (PMID 38967628, 2024). "The lack of significant differences in cell density between the center and the margin of the tumor for CD8-, CD68-, and CD163-positive cells suggests a relatively uniform distribution of immune cells within the selected cores." (PMID 39338178, 2024). "In contrast, M2 macrophages, characterized by both CD68 and CD163 expression, are considered to promote tumor growth and metastasis by releasing chemokines, which are inflammatory growth factors." (PMID 39594814, 2024). "Expression of TGFβ on tumor cells resulted in higher density of cells expressing TGFβ as compared to the density of cells co-expressing CD3 and TGFβ or CD68 and TGFβ." (PMID 39516662, 2024).